BRDT (bromodomain testis associated)
Description:
Testis-specific chromatin protein that specifically binds histone H4 acetylated at 'Lys-5' and 'Lys-8' (H4K5ac and H4K8ac, respectively) and plays a key role in spermatogenesis. Required in late pachytene spermatocytes: plays a role in meiotic and post-meiotic cells by binding to acetylated histones at the promoter of specific meiotic and post-meiotic genes, facilitating their activation at the appropriate time. In the post-meiotic phase of spermatogenesis, binds to hyperacetylated histones and participates in their general removal from DNA. Also recognizes and binds a subset of butyrylated histones: able to bind histone H4 butyrylated at 'Lys-8' (H4K8ac), while it is not able to bind H4 butyrylated at 'Lys-5' (H4K5ac) (By similarity). Also acts as a component of the splicing machinery in pachytene spermatocytes and round spermatids and participates in 3'-UTR truncation of specific mRNAs in post-meiotic spermatids (By similarity). Required for chromocenter organization, a structure comprised of peri-centromeric heterochromatin.
Synonyms: CT9; BRD6; SPGF21
Tractability: Small molecule: a drug acting on it is in phase 2 or 3 trials; a structure with a bound ligand is known; a high-quality ligand is known; it belongs to a druggable protein family. PROTAC: it is named in the literature on targeted protein degradation; UniProt records ubiquitination sites on it; ubiquitination databases record sites on it; a small molecule that binds it is known.
Target class: Epigenetic regulator; Bromodomain; Reader
Chemical probes: (+)-JQ1 (high quality), ABBV-744 (high quality), AZD-5153 (high quality), GSK046 (high quality), GSK620 (high quality), GSK789 (high quality), GSK973 (high quality), I-BET151 (high quality), MT1 (high quality), PFI-1 (high quality), Pelabresib anhydrous (high quality), biBET (high quality), bromosporine (high quality), iBET-BD1 (high quality)
Gene: Protein-coding gene on chromosome 1 (91,949,343 to 92,014,426, forward strand). Ensembl gene ENSG00000137948.
Subcellular location: Nucleus
Gene Ontology:
Molecular function: histone binding; chromatin binding; protein serine/threonine kinase activity; transcription coactivator activity; histone H4 reader activity
Biological process: regulation of DNA-templated transcription; chromatin remodeling; male meiosis I; male meiotic nuclear division; positive regulation of gene expression; regulation of RNA splicing; regulation of transcription by RNA polymerase II; sperm DNA condensation; positive regulation of DNA-templated transcription; spermatogenesis
Cellular component: nucleus; chromatin
Genetic constraint (gnomAD): Loss-of-function variants: 61 observed, 94.28 expected, observed/expected ratio (o/e) 0.65, 90% interval 0.53 to 0.8. The upper end of that interval is the gene's LOEUF score, 0.8, which puts it in group 3 of 6, group 1 being the genes least tolerant of losing a copy. Missense variants: 875 observed, 979.4 expected, observed/expected ratio (o/e) 0.89, 90% interval 0.84 to 0.94. Synonymous variants: 302 observed, 331.74 expected, observed/expected ratio (o/e) 0.91, 90% interval 0.83 to 1.
Homologues: Orthologues: chimpanzee BRDT (99% identical), macaque BRDT (96% identical), dog BRDT (81% identical), rabbit BRDT (79% identical), pig BRDT (78% identical), mouse Brdt (73% identical), rat Brdt (71% identical), tropical clawed frog cecr2 (13% identical), Caenorhabditis elegans baz-2 (8% identical), Drosophila melanogaster Acf (8% identical). Paralogues in human: BRD4 (47% identical), BRD2 (38% identical), BRD3 (38% identical), CECR2 (17% identical), BPTF (14% identical), BAZ2B (11% identical), BAZ1B (10% identical), BAZ1A (10% identical), BAZ2A (10% identical), KAT2B (7% identical), KAT2A (7% identical).
Diseases named in the same sentence as BRDT in open-access papers:
BRDT is named in the same sentence as 41 diseases in open-access papers, as found by Europe PMC text mining. Sharing a sentence is not in itself a finding about the gene and the disease. The quoted sentences say what the papers report.
Infertility (5 papers, 2016 to 2024). "Pan-BETi was also reported to have activity for bromodomain testis-specific protein (BRDT), causing testicular atrophy and reversible infertility." (PMID 32366905, 2020). "BRDT-Knock-out mice exhibited infertility with complete absence of post-meiotic cells." (PMID 38310235, 2024).
esophageal squamous cell carcinoma (4 papers, 2021 to 2023). Esophageal squamous cell carcinoma (ESCC) is a type of esophageal carcinoma (EC) that can affect any part of the esophagus, but is usually located in the upper or middle third. "On the contrary, the testis-specific protein BRDT directs super-enhancer activity in a subset of esophageal squamous cell carcinoma (ESCC)." (PMID 34540900, 2021).
male infertility (4 papers, 2012 to 2025). The inability of the male to effect fertilization of an ovum after a specified period of unprotected intercourse. "Studies in humans have identified polymorphisms in the BRDT gene that are significantly associated with impaired spermatogenesis and male infertility, suggesting that BRDT may contribute to idiopathic male infertility and could also be a potential druggable target for male contraception." (PMID 29513658, 2018). "The testis-specific bromodomain protein BRDT recognizes acetylated H4 tails to drive chromatin reorganization and interacts with the SWI/SNF subunit SMARCE1; disruption of BRDT function leads to male infertility." (PMID 41354937, 2025).
breast carcinoma (2 papers, 2020 to 2022). "Some studies indicated that EIF4EBP1 is involved in the progression of various cancer types (including renal cell carcinoma, breast cancer) through regulating the transcription level of BRDT." (PMID 35186763, 2022). "BRD2, a member of the bromodomain and extra-terminal (BET) family including mammalian BRD3, BRD4 and BRDT, is remarkably over-expressed in breast cancer, gastric cancer (GC), malignant pleural mesothelioma (MPM) and castration-resistant prostate cancer (CRPC)." (PMID 32927435, 2020).
esophageal cancer (2 papers, 2019 to 2021). A primary or metastatic malignant neoplasm involving the esophagus. "We next investigated whether BRDT was preferentially expressed in a certain histological subtype of esophageal cancer and found BRDT to be preferentially expressed in ESCC." (PMID 33658703, 2021).
prostate carcinoma (2 papers, 2024 to 2025). A carcinoma that arises from epithelial cells of the prostate gland. "Among these targets, five of them (A2AR/ADORA2A, CSK, CYP24A1, BRDT, and BRAF) have been suggested in recent scientific papers to be related to prostate cancer and all can interact with ligands with known therapeutic advantages against advanced prostate cancer." (PMID 38983753, 2024).
acephalic spermatozoa syndrome (1 paper, 2021). "BRDT, DNAH6, CEP112, and HOOK1 have also been reported to be associated with acephalic spermatozoa syndrome." (PMID 34422805, 2021).
Alzheimer disease (1 paper, 2017). A progressive, neurodegenerative disease characterized by loss of function and death of nerve cells in several areas of the brain leading to loss of cognitive function such as memory and language. "Here we tested the effect of JQ1—a small-molecule inhibitor of the chromatin readers BRD2, BRD3, BRD4 and BRDT—on brain function and show that JQ1 is able to enhance cognitive performance and long-term potentiation in wild-type animals and in a mouse model for Alzheimer’s disease." (PMID 28949335, 2017).
breast tumor (1 paper, 2022). "Despite this, BRD2, BRD3, and BRDT expression were discovered to be low in normal breast tissues, while it was shown to be high and medium in the cytoplasmic and membranous parts of breast tumor tissues, respectively." (PMID 35371325, 2022).
cryptorchidism (1 paper, 2025). The failure of one or both testes of a male fetus to descend from the abdomen into the scrotum during the late part of pregnancy. "In addition, we confirmed two key DE-FRGs, BRDT and PARP11, by integrating the DEGs associated with spermatogenesis, which were downregulated in AdMinus testes of patients with cryptorchidism." (PMID 40454210, 2025). "Overall, we deduced that BRDT and PARP11 downregulation in patients with cryptorchidism may hinder spermatogenesis, which could be used as a reference for early therapeutic strategies for patients with cryptorchidism." (PMID 40454210, 2025). "Gene Set Enrichment Analysis, ROC and IHC analyses were conducted and the results revealed that BRDT and PARP11 might play critical roles in spermatogenesis dysfunction in patients with cryptorchidism." (PMID 40454210, 2025). "In conclusion, our study revealed that BRDT and PARP11 were downregulated in AdMinus testes of cryptorchidism, which suggested that ferroptosis might play a significant role in spermatogenic dysfunction in cryptorchidism." (PMID 40454210, 2025).
melanoma (1 paper, 2020). A malignant, usually aggressive tumor composed of atypical, neoplastic melanocytes. "BET protein consists of BRDT, BRD2, BRD3, and BRD4, among which BRD4 is mainly involved in melanoma progression." (PMID 33052224, 2020).
Obesity (1 paper, 2018). Accumulation of substantial excess body fat. "Among the genes affiliated with the 119 significant CpGs, SOCS3 and DOK2 were differentially expressed in the SAT of obesity patients, while seven genes (SOCS3, PRR5L, ABCG1, BRDT, B3GNT7, ZNF710, and RARRES1) were differentially expressed in the VAT of obesity patients." (PMID 30619480, 2018).
osteoporosis (1 paper, 2016). A condition of reduced bone mass, with decreased cortical thickness and a decrease in the number and size of the trabeculae of cancellous bone (but normal chemical composition), resulting in increased fracture incidence. "Recently, we showed that NMP acts as a low affinity bromodomain inhibitor for BRD2, BRD3, BRD4, and BRDT and has potential for osteoporosis treatment." (PMID 27110299, 2016).
pancreatic cancer (1 paper, 2021). "This regulatory mechanism is similar to what we have previously shown for BRD4, the closest paralog to BRDT, which localizes to lineage-specific enhancers to regulate genes that are crucial for lineage specification and pancreatic cancer subtype." (PMID 33658703, 2021). "Given our findings that BRDT colocalized with ΔNp63 on several genes such as FAT2 and PTHLH, which we previously demonstrated as being associated with ΔNp63-dependent SEs in pancreatic cancer, we investigated whether BRDT, like BRD4, may be a defining feature of SEs in a subset of ESCC." (PMID 33658703, 2021).
spermatogenesis impairment (1 paper, 2021). "Moreover, another bromodomain protein, bromodomain testis-specific protein (BRDT), has been reported to be involved in susceptibility to spermatogenesis impairment in humans." (PMID 34470615, 2021).
cancer (11 papers, 2018 to 2025). A tumor composed of atypical neoplastic, often pleomorphic cells that invade other tissues. "Mechanistically, we demonstrate for the first time that BRDT occupancy is associated with the activity of a select set of cancer subtype-specific genes." (PMID 33658703, 2021). "The BET family is composed by BRD2, BRD3, BRD4, and BRDT, and plays important roles in cancer by directly regulating the expression of cancer-related genes such as MYC, and the transcription factor NF-κB." (PMID 41551874, 2025). "BET proteins (BRD2, BRD3, BRD4 and BRDT) serve as the readers of DNA acetylation and regulate the expression of key genes in cancer." (PMID 38893083, 2024). "The transcriptional levels of BET (BRD1,BRD2,BRD3, BRD4 and BRDT) were compared between cancer and normal samples in GEPIA database." (PMID 36711038, 2023). "Mechanistically, BRDT colocalizes and cooperates with ΔNp63, a defining factor of the squamous subtype in cancer, to drive the expression of a subset of ΔNp63-dependent genes." (PMID 33658703, 2021). "Furthermore, both entities displayed a shared regulation of genes, including MYC, PHGDH, FBXO2 and BRDT, which promote cancer progression according to previous studies." (PMID 38725048, 2024). "Although pan-BET inhibitors are being tested in clinical trials for several different malignancies including lymphoma, breast cancer, and prostate cancer, the biological understanding of the different BET family members, especially BRD2, BRD3, and BRDT, in cancer is still very limited." (PMID 33658703, 2021). "Interestingly, BRDT was also reported to be ectopically expressed in cancer two decades ago, but its function in tumorigenesis has remained elusive until now." (PMID 33658703, 2021). "However, neither study revealed the underlying mechanism by which BRDT functions in cancer." (PMID 33658703, 2021). "By contrast, in human PDA tumors, containing cancer and stromal cell types, nearly all HDACs (except SIRT4) and BETs (except BRDT, BRWD3, and CECR2) were highly expressed." (PMID 33244070, 2020). "Taken together, these findings reveal a previously unknown function of BRDT in ESCC and provide a proof-of-concept that BRDT may represent a novel therapeutic target in cancer." (PMID 33658703, 2021). "Moreover, using data from the Cancer Cell Line Encyclopedia we identified two BRDT-positive (KYSE180 and TE6) and two BRDT-negative ESCC cell lines (KYSE70 and KYSE150) and confirmed BRDT expression in KYSE180 and TE6 cells." (PMID 33658703, 2021).
tumor (6 papers, 2019 to 2024). "The results indicated that the expression levels of BRD2, BRD3, BRD4 were higher in GBM tumor tissues than those in normal tissues, and BRDT expression in tumor was lower than that in normal tissues." (PMID 36711038, 2023). "Two recent studies published during the revision of this work showed a role of BRDT in regulating tumor growth both in vitro and in vivo, highlighting the clinical potential of BRDT." (PMID 33658703, 2021). "Importantly, consistent with the functional importance of BRDT in controlling tumor cell migration, BRDT overexpression in KYSE150 increased cell migration and this effect was blocked by depleting ΔNp63." (PMID 33658703, 2021). "Therefore, despite the potential utility of small-molecule inhibitors or PROTACs in blocking BET protein function, it is currently unclear whether the inhibition or depletion of BRDT activity would be sufficient to impede ESCC tumor growth." (PMID 33658703, 2021).
BRDT also shares sentences with these, for which no sentence is quoted: Sepsis (2 papers); viral infection (2); ACTHomas (1); atherosclerosis (1); Azoospermia (1); bacterial infections (1); cardiovascular diseases (1); chronic myeloid leukemia (1); gastric cancer (1); head and neck cancer (1); heart failure (1); infection (1); lung adenocarcinoma (1); lung carcinoma (1); lung squamous cell carcinoma (1); malignant pleural mesothelioma (1); non-small cell lung carcinoma (1); pulmonary arterial hypertension (1); renal cell carcinoma (1); squamous carcinoma (1); Testicular atrophy (1); testicular cancer (1); testicular germ cell tumor (1); uterine carcinosarcoma (1).